KLK6 (kallikrein related peptidase 6)
Diseases named in the same sentence as KLK6 in open-access papers (continued):
Sharing a sentence is not in itself a finding about the gene and the disease.
Atrophy (1 paper, 2016). Any weakening or degeneration, especially through lack of use. "We used KLK6 knockout (KO) mice to evaluate KLK6 role in skin regeneration after steroid-induced atrophy." (PMID 27283773, 2016). "Even though the mechanisms of skin regeneration after steroid-induced atrophy are not well known, the induction of KLK6 seems to be common for both wound healing and the regeneration after steroids." (PMID 27283773, 2016).
bowel obstruction (1 paper, 2012). "The subsequent dramatic elevation of both KLK6 and S100B proteins after 170 hours, may be associated with the suffered bowel obstruction." (PMID 23049835, 2012).
carcinoma in situ (1 paper, 2014). "For instance, four patient samples had ICD9 code 233.1 (carcinoma in situ) and three of them (samples #109, #110, and #116) had S100A7 genes up-regulated and another set (samples #110, #111, and #116) had KLK6 up-regulated in normal to LGSIL pairs." (PMID 25505737, 2014).
cervical (1 paper, 2014). "In particular, S100A7 and KLK6 genes were differentially expressed during progression from normal tissue to LGSIL in 3/6 samples and could be key members of signature networks in cervical pre-cancer progression." (PMID 25505737, 2014).
chromophobe renal cell carcinoma (1 paper, 2018). Chromophobe renal cell carcinoma is a rare subtype of renal cell carcinoma, originating from the intercalating cells of the collecting ducts and macroscopically manifesting as a well-circumscribed, highly lobulated, solid tumor that is usually diagnosed at an early stage. "Chromophobe renal cell carcinoma had increased expression of the following KLKs: KLK1 (32-fold), KLK2 (12-fold), KLK3 (69-fold), KLK4 (234-fold), KLK15 (132-fold), whereas decreased expression of KLK5 (5-fold), KLK6 (13-fold), and KLK7 (26-fold)." (PMID 29707153, 2018).
Cirrhosis (1 paper, 2021). A chronic disorder of the liver in which liver tissue becomes scarred and is partially replaced by regenerative nodules and fibrotic tissue resulting in loss of liver function. "KLK6 also was shown to induce de novo cirrhosis and was increased in HCC tissues." (PMID 34359689, 2021). "The IHC suggests that KLK6 increase with cirrhosis and HCC while MEP1A decrease in cirrhosis and HCC." (PMID 34359689, 2021). "The gradient staining confirmed the predicted activity, showing that KLK6 increases with cirrhosis and HCC, and MEP1A decreases in cirrhosis and HCC." (PMID 34359689, 2021).
clear cell renal cell carcinoma (1 paper, 2018). "Renal clear cell carcinoma had two KLKs with classification power above the AUC threshold (KLK1: 0.921, KLK6: 0.928)." (PMID 29707153, 2018). "The renal papillary carcinoma and renal clear cell carcinoma had dramatically decreased expression of KLK1 (52-fold and 94-fold), KLK6 (45-fold and 42-fold) and KLK7 (33-fold and 48-fold), respectively." (PMID 29707153, 2018).
cognitive decline (1 paper, 2018). "Increased plasma levels of KLK6 in these individuals also correlated with lower MMSE scores, supporting the notion that an increase in plasma KLK6 levels might be associated with cognitive decline." (PMID 29378650, 2018).
colitis (1 paper, 2024). Inflammation of the colon. "The pathology analysis revealed that CPC;Apcfl/fl;Klk6+/+, CPC;Apcfl/fl;Klk6+/fl, and CPC;Apcfl/fl;Klk6fl/fl mice had mild subacute multifocal colitis with mixed lymphocytic and neutrophilic infiltrates in the colon but not in the small intestine." (PMID 39594797, 2024).
delirium (1 paper, 2021). A disorder characterized by confusion; inattentiveness; disorientation; illusions; hallucinations; agitation; and in some instances autonomic nervous system overactivity. "Sustained elevations in TDP43, YKL40, and KLK6 may suggest potential links to delirium, increased psychoactive disorders, and atypical dementias in the wake of COVID-19." (PMID 34944606, 2021).
depression (1 paper, 2023). "Interestingly, reduced KLK6 gene expression was also observed in the PFCTX of patients diagnosed with depression, which may suggest a potential correlative role in this disorder." (PMID 38235150, 2023).
dermatitis (1 paper, 2024). An inflammatory process affecting the skin. "Using ELISA, we examined IL-17C protein expression in several Ps animal models of psoriasiform-like dermatitis, including the KC-Tie2 mouse model, the topical imiquimod treated C57BL/6 mice, the Klk6+ model, and a model in which Il17c is genetically overexpressed in KCs." (PMID 38470486, 2024).
gastric tumor (1 paper, 2016). "Analysis of 59 human gastric tumors showed KLK6 upregulation at stages III and IV, but low-level expression at stages I and II." (PMID 27863404, 2016). "To determine whether KLK6 expression is regulated by transcription factors in gastric tumors during the autophagic process, we performed ChIP analysis of the KLK6 promoter." (PMID 27863404, 2016). "Further, overexpression of KLK6 in a xenograft model induced AF-induced chemoresistance, autophagosome formation, and the synthesis and activation of LC3B in mouse gastric tumor tissue." (PMID 27863404, 2016).
hemorrhage (1 paper, 2012). Loss of blood from the vascular compartment to the exterior or into nonvascular body space as a result of rupture or severance of the blood vessels. "The initial concentration after patient hospitalization (<12 hours form the event) and KLK6 levels within the 2–3 days after hemorrhage seem to be the most informative in classifying patients according to their outcome, perhaps reflecting the extent of the initial brain damage suffered." (PMID 23049835, 2012).
Horseshoe kidney (1 paper, 2025). A connection of the right and left kidney by an isthmus of functioning renal parenchyma or fibrous tissue that crosses the midline. "The primary objective of the present study is to investigate the spatial and temporal expression pattern of KLK6, as well as AQP1 and AQP2, in the cortex of the kidney throughout normal human nephrogenesis and CAKUT: duplex kidneys, horseshoe kidneys, and dysplastic kidneys." (PMID 40428321, 2025). "The primary objective of the present study is to investigate the spatio-temporal expression patterns of KLK6, AQP1, and AQP2 throughout normal human nephrogenesis and congenital kidney and urinary tract (CAKUT) abnormalities: duplex kidneys, horseshoe kidneys, and dysplastic kidneys." (PMID 40428321, 2025).
hydronephrosis (1 paper, 2025). Collection of urine in the renal pelvis that results in dilatation of the renal pelvis and calyces. "Structural abnormalities, such as ureteral obstruction, hydronephrosis, or altered nephron distribution, could create localized hypoxia, inflammation, or mechanical stress in duplex kidneys, which may upregulate KLK6 as part of a reparative or inflammatory response." (PMID 40428321, 2025). "In duplex kidneys, structural abnormalities such as ureteral obstruction and hydronephrosis may upregulate KLK6 as part of a reparative response, while its downregulation could impair epithelial remodeling and cytoskeletal integrity, exacerbating dysplastic phenotypes." (PMID 40428321, 2025).
Immunodeficiency (1 paper, 2011). Failure of the immune system to protect the body adequately from infection, due to the absence or insufficiency of some component process or substance. "Since insufficient lymphocyte apoptosis is a well known participant in autoimmune and lymphoproliferative disease, but in excess can promote immunodeficiency, approaches that target KLK6 may hold new promise for the treatment of diseases with an inflammatory substrate." (PMID 21464892, 2011).
intestinal tumor (1 paper, 2024). "However, the role of KLK6 in intestinal tumor development in vivo is still unknown." (PMID 39594797, 2024).
laryngeal squamous cell carcinoma (1 paper, 2015). A squamous cell carcinoma that arises from the larynx. "To address the clinical relevance of these findings, we determined KLK6 protein levels by IHC staining on tissue microarrays (TMAs) containing tissue samples of two patient cohorts with primary oropharyngeal (OPSCC) or laryngeal squamous cell carcinoma (LSCC)." (PMID 25990935, 2015).
mucinous adenocarcinoma (1 paper, 2009). An invasive adenocarcinoma composed of malignant glandular cells which contain intracytoplasmic mucin. "Shown here is strong staining for both KLKs in serous adenocarcinoma, with KLK6 shown expressed in a mucinous adenocarcinoma and KLK13 expression in a clear cell tumour." (PMID 19707197, 2009).
oral cancers (1 paper, 2015). "The serine protease, KLK6, is also overexpressed by more than 25-fold in rat oral cancers induced by 4-NQO." (PMID 25635769, 2015). "Based on the overexpression of KLK6 in both rat OSCC and several types of human malignancies, a similar argument can be made in support of further oral cancer chemoprevention studies with serine protease inhibitors." (PMID 25635769, 2015). "Although differential expression of KLK6 in human oral cancers has not been reported, KLK6 is significantly upregulated in cancers of the colon and several other sites in humans." (PMID 25635769, 2015).
ovarian adenocarcinoma (1 paper, 2009). An adenocarcinoma that arises from the ovary. "Both KLK6 and KLK13 showed staining in all types of ovarian adenocarcinoma." (PMID 19707197, 2009).
renal failure (1 paper, 2025). "Clinical studies suggest that circulating KLK6 levels positively correlate with serum creatinine concentrations in patients with renal failure, indicating its potential utility in assessing kidney function." (PMID 40428321, 2025).
salivary gland diseases (1 paper, 2023). "Further exploration of the inhibitory effect of testosterone on Klk6 and Klk7 expression, and their potential impact on susceptibility to salivary gland diseases, also warrants careful consideration in future studies." (PMID 38203721, 2023).
stomach adenocarcinoma (1 paper, 2018). "In stomach adenocarcinoma, the only significant change in expression was found in KLK6 (11-fold upregulated)." (PMID 29707153, 2018).
Stroke (1 paper, 2023). Sudden impairment of blood flow to a part of the brain due to occlusion or rupture of an artery to the brain. "Our study design is not suitable to elucidate this inverse relationship specifically, however, it has described that Kallikrein Related Peptidase 6 (KLK6) and Plasminogen activator inhibitor (PAI) are decreased during subarachnoid bleeding and 1-week after stroke, respectively." (PMID 36653383, 2023).
varicella zoster infection (1 paper, 2022). A highly contagious viral infection caused by the varicella zoster virus. "These inhibitors are now freely available to be used to investigate the role of KLK6 in varicella zoster infection, as well as in other pathological indications." (PMID 36320846, 2022).
tumor (77 papers, 2002 to 2026). "KLK6 is considered to be associated with proliferation, adhesion, and malignant transformation of tumor tissue, being an important factor responsible for poor prognosis." (PMID 40156045, 2025). "The specific enrichment of KLK6 in malignant cells underscores its potential as a target for precision therapy, as kallikrein family members have been implicated in tumor progression and immune modulation." (PMID 41383634, 2025). "It is suggested that the tumor-specific loss of KLK6 expression is due to increased DNA methylation at the KLK6 promoter." (PMID 37345019, 2023). "In vitro and in vivo experimental measurements, including CCK8, transwell migration, TUNEL, and nude mouse transplanted tumor model, were used to evaluate the antineoplastic activities of KLK6 loss-of-function." (PMID 36193495, 2022). "Immunohistochemistry analysis of tissue sections of ovarian and melanoma patients found the overexpression of KLK6 in tumor associated stromal cells and keratinocytes." (PMID 35222418, 2022). "Our mRNA and protein expression analyses using two different PDAC patient cohorts demonstrate that high KLK6 levels in tumour and immune cells are significantly linked to poor prognosis." (PMID 34439122, 2021). "The mutational landscape in the KLK6-high group suggests the possibility of utilizing the tumor mutational burden (TMB) biomarker for estimating the therapy outcomes in the CRC patients with high KLK6 expression." (PMID 34065672, 2021). "These samples were outliers with respect to KLK6 expression and the intent was to compare two distinct expression group of samples for identification of KLK6 expression associated biomarkers in tumor samples." (PMID 34065672, 2021). "Overall, our mRNA and protein expression data indicate that high KLK6 levels in tumour and immune cells are significantly linked to poor prognosis, while KLK6 levels in the stroma had no prognostic impact." (PMID 34439122, 2021). "Upregulation of KLK6 was also believed to be associated with high depth of tumor invasion, presence of distant metastases, and as an independent prognosticator to predict poor disease-free and overall survival in CRC patients." (PMID 32630086, 2020). "KLK6 can degrade components of the extracellular matrix, and is implicated in tissue remodeling and the induction of tumor-relevant processes such as proliferation, migration, and invasion." (PMID 28671620, 2017). "For example, high KLK5 and KLK6 tumor tissue levels are associated with an advanced disease stage and significantly shorter progression-free survival (PFS) and overall survival (OS) times." (PMID 25436002, 2015). "Specifically, higher tumor core levels of KLK6, KLK7 and KLK9 were each associated with reduced GBM patient survival." (PMID 26231762, 2015). "In univariate analysis, patients with high KLK6 expression had a greater risk of recurrence (P=0.004) than patients with low KLK6 expressing tumours." (PMID 19707197, 2009). "KLK6 encodes a serine protease, part of the kallikrein family, which is also highly expressed in several cancers, including breast, ovarian, and CRCs, promoting tumor cell invasion and migration." (PMID 40932351, 2026). "A previous analysis of the kallikrein-related peptidase family in CRC tumor samples from the TCGA database revealed that KLK6 overexpression in human tumors is associated with the overexpression of other members of the kallikreins protease family, i.e., KLK7, KLK8, and KLK10." (PMID 39594797, 2024). "Our findings suggest that KLK6 may participate in the carcinogenesis of BLCA via enriching tumor-associated immunocytes." (PMID 36193495, 2022).
tumor (continued). "In pancreatic ductal adenocarcinoma, immunostaining analysis of epithelial tumor cells and the surrounding stroma and immune cells showed that high KLK6 protein levels in the tumor and immune cells are significantly associated with shorter survival compared to low protein levels." (PMID 35222418, 2022). "Combining preclinical models with machine learning approaches that utilise large databases and experimental data may identify tumour cell responses to therapeutic agents, for example by linking treatment responses to the mutational status of KLK6." (PMID 34439122, 2021). "High KLK6 levels in tumour and CD68+ cells were linked to shorter survival." (PMID 34439122, 2021). "Moreover, KLK6 is implicated in tissue remodeling and induction of tumor-relevant processes such as proliferation, migration and invasion." (PMID 25990935, 2015). "In addition, an increased percent of tumor immunoreactive for KLK6 or KLK9 was associated with decreased survival in grade IV patients." (PMID 26231762, 2015). "However, it is worth noting that the tumor promoting function of KLK6 in most human cancers has been deduced from the association of its expression and clinical or pathological features." (PMID 25990935, 2015). "However, the pathogenic role of KLK6 in the tumor microenvironment remains unclear; moreover, little is known about how KLK6 contributes to cross-talk between cancer cells and inflammatory cells." (PMID 36552865, 2022). "Consequently, nuclear accumulation of β-catenin might result from down-regulation of E-cadherin during EMT after silencing of KLK6 in vitro or loss of E-cadherin expression in KLK6low tumor cells during malignant progression of HNSCCs." (PMID 25990935, 2015). "In HNSCC, a tumor suppressor function is supported by showing that knockdown of KLK6 led to increased proliferation, migration, invasion, epithelial-to-mesenchymal transition markers, and survival post-radiation." (PMID 41597241, 2026). "The results showed that compared to LCC, the density of EPCAM+KLK6+ double-positive cells was significantly higher in RCC tumor tissues." (PMID 40932351, 2026). "KLK6 expression was markedly elevated in malignant epithelial cells and increased with advancing tumor stage." (PMID 41383634, 2025). "In head and neck squamous cell cancer (HNSCC) cancer, a tumor suppressor function is supported by showing that knockdown of KLK6 led to increased proliferation, migration, invasion, epithelial-to-mesenchymal transition markers and survival post radiation." (PMID 41509368, 2025). "Studies on KLK6 and CRC have revealed significantly high KLK6 expression in CRC tissues as compared to normal tissues, which is associated with tumor serosa infiltration, liver metastasis, clinical stage, and poor prognosis." (PMID 40156045, 2025). "Nevertheless, our ability to detect KLK6 protein in the adenomatous areas of the mouse colon using a highly accurate OCT/LEF imaging with fluorophore-labeled KLK6 antibody demonstrated the potential future application of KLK6 as a tumor marker." (PMID 39594797, 2024). "To enhance our understanding of KLK6’s role in mutant APC-driven CRC tumor development, we analyzed KLK6 expression in the intestinal tract of the ApcMin/+ mouse." (PMID 39594797, 2024). "The analysis of the kallikrein-related peptidase family in CRC tumor samples from The Cancer Genome Atlas (TCGA) database identified a distinct pattern of overexpression of KLK6 along with elevated expression of KLK7, KLK8, and KLK10." (PMID 39594797, 2024). "Further, the serine protease Kallikrein-6 (KLK6) facilitate tumor invasion by degrading the extracellular matrix." (PMID 38350915, 2024). "The differential gene expression levels between the tumor and adjacent tissue showed that KLK6 and KLK7 expression levels were higher in normal tissues than in tumors." (PMID 38137332, 2023). "The oligodendrocyte marker genes OPALIN, MAG, and KLK6 are up-regulated in tumor cells and down-regulated in the periphery." (PMID 35327982, 2022).